TNF (tumor necrosis factor)
Diseases named in the same sentence as TNF in open-access papers (continued):
Sharing a sentence is not in itself a finding about the gene and the disease.
Insulin resistance (continued). "The association between the increase in LCN2 concentrations and the development and severity of T2D can be explained through the evidence that demonstrates that LCN2 stimulates the increase of TNF-a and IL-6, cytokines that have been widely recognized as inducers of insulin resistance." (PMID 39808380, 2025). "Moreover, TNF-α has been demonstrated to increase glucose and triglyceride production in the liver, meanwhile leading to insulin resistance by a reduction in peripheral glucose uptake in response to insulin." (PMID 40362446, 2025). "When compared to IL-6, TNF-α appears to have a more direct effect on insulin resistance." (PMID 40385768, 2025). "Studies suggest that in overweight or obese women, visceral adipocytes release inflammatory cytokines like tumor necrosis factor α (TNF-α) and interleukin 6 (IL-6), which contribute to insulin resistance and activate the inflammasome pathway, thus exacerbating PCOS symptoms." (PMID 41411269, 2025). "Furthermore, TNF-α treatment had a more pronounced effect on IS cells, reflecting the higher baseline levels of these cytokines in insulin resistance status." (PMID 41574186, 2025). "Additionally, SNPs in genes encoding cytokines such as TNF-α (rs1800629) and IL-6 (rs1800795) have been implicated in the chronic low-grade inflammation characteristic of GDM, exacerbating insulin resistance and metabolic dysfunction." (PMID 40076938, 2025). "Dilated and inflamed visceral adipose tissue releases a variety of molecules, including interleukin-6, tumor necrosis factor-alpha, and other pro-inflammatory cytokines, which may contribute to the pathogenesis of insulin resistance and kidney injury." (PMID 40339352, 2025). "Factor 1, representing a pro-inflammatory cytokine response (primarily TNF-α and IL-8), was positively associated with changes in HOMA-IR (r = 0.38; p = 0.02), indicating that higher levels of inflammation were linked to increased insulin resistance." (PMID 41156500, 2025). "Adipose tissue macrophages secrete TNF-α, which plays a crucial role in insulin resistance." (PMID 39803918, 2025). "In addition, insulin resistance promotes the production and secretion of pro-inflammatory adipokines, such as interleukin-6 (IL-6) and tumor necrosis factor-α (TNF-α)." (PMID 40290665, 2025). "By targeting TNF-α with pharmacological drugs or lifestyle changes, we may find an effective way to alleviate the inflammatory processes contributing to insulin resistance and metabolic syndrome." (PMID 40002771, 2025). "In metabolic tissues, TNF-α interferes with insulin receptor signaling by promoting serine phosphorylation of insulin receptor substrate-1, a change that reduces downstream insulin action and contributes to insulin resistance, a core metabolic feature of PCOS." (PMID 41561267, 2025). "The underlying mechanisms may involve multiple pathways: Firstly, insulin resistance induced by elevated TyG levels promotes macrophage polarization toward a pro-inflammatory phenotype, leading to the release of cytokines such as TNF-α and IL-6." (PMID 41024162, 2025). "Dietary patterns directly affect metabolic and inflammatory status - for example, excess intake of saturated fats and refined sugars promotes obesity, insulin resistance, and dyslipidaemia, which in turn amplify pro-inflammatory cytokines such as IL-6 and TNF-α." (PMID 41280310, 2025). "Studies also reported that TNF-α levels may vary based on BMI, metabolic phenotype, and severity of insulin resistance." (PMID 40385768, 2025). "Since adiponectin is an insulin-sensitizing hormone, reduced levels because of heightened TNF-α activity may further increase insulin resistance in GDM." (PMID 40722699, 2025). "Furthermore, pro-inflammatory cytokines such as IL-6 and TNF-α also contribute to insulin resistance." (PMID 40429815, 2025).
Insulin resistance (continued). "Indeed, TNF-α induces insulin resistance through mechanisms such as increased serine phosphorylation of IRS-1, which impairs insulin receptor tyrosine kinase activity and insulin signal transduction." (PMID 41574186, 2025). "It further reduces IL-8 expression and modulates pathways associated with inflammation, UV-induced mutagenesis, and insulin resistance by targeting insulin-like growth factor-1 (IGF-1) and tumor necrosis factor alpha (TNF-α), particularly relevant to colorectal cancer." (PMID 40909085, 2025). "However, in chronic conditions such as obesity, insulin resistance, or autoimmune diseases, TNF-α can remain persistently elevated, albeit at lower levels compared to acute inflammation." (PMID 40004236, 2025). "Additionally, tumour necrosis factor-α (TNF-α) is secreted from macrophages and impairs insulin signalling, leading to insulin resistance." (PMID 39803918, 2025). "Additionally, adipocytes have the capability to release pro-inflammatory cytokines like TNF-α and IL-1β, which are factors contributing to the development of insulin resistance." (PMID 39606781, 2024). "Furthermore, Gunawan and collaborators showed that in obese and insulin-resistant rats, treatment with 200 mg/kg/day of 6-gingerol increased adiponectin concentrations and decreased TNFα levels in adipose tissue." (PMID 39334752, 2024). "Infiltrated macrophages release TNF-α, which can induce insulin resistance in adipocytes." (PMID 38257186, 2024). "Besides inducing insulin resistance, this interplay between TNF- α and Cers amplifies mitochondrial reactive oxygen species production, thereby promoting apoptosis." (PMID 38561799, 2024). "White adipose tissue stresses or lipopolysaccharides increase NF-κB and c-Jun N-terminal kinase signaling, upregulate the production of inflammatory cytokines such as TNF-α and IL-6, and promote insulin resistance in adipocytes and macrophages via TLR4/TLR2 activation." (PMID 38292473, 2024). "PTSD is associated with elevated levels of inflammatory markers, including CRP, interleukin-6 (IL-6), and tumor necrosis factor-alpha (TNF-α), that could exacerbate insulin resistance." (PMID 38646205, 2024). "As it is known, TNF-α is a multifunctional cytokine involved in many cellular and biological processes such as immune function, cell differentiation, apoptosis, and energy metabolism, also, it was reported that TNF-α can induce a state of insulin resistance in adipocytes." (PMID 38820505, 2024). "Moreover, excessive adipose tissue deposition promotes insulin resistance, impaired glucose and lipid metabolism, and systemic inflammatory reactions, including the release of interleukins (IL‐6, 10, 13, 14), TNF, and diffuse macrophage activation." (PMID 38767024, 2024). "Moreover, significant reductions in the TNF-α, IL-6, MDA, and COX-2 levels confirmed that inflammation and oxidative stress have been associated with insulin resistance." (PMID 38892660, 2024). "To further confirm whether the 12 h TNF-α/24 h hypoxia model of adipocyte inflammation/insulin resistance could be maintained as a long term model, we assessed the insulin stimulated glucose uptake at 48 h and 72 h." (PMID 39415617, 2024). "The levels of TNF-α are closely related to the extent of overweight and insulin resistance." (PMID 39149648, 2024). "For example, TNF-α is thought to be involved in the development of insulin resistance, where dysregulation of glucose metabolism may promote the development of sepsis." (PMID 38773119, 2024). "Network pharmacology studies exploring the mechanism of DCHD in preventing and treating NAFLD have revealed its potential association with the tumor HIF-1 signaling pathway, tumor necrosis factor (TNF) signaling pathway, insulin resistance pathway, among others." (PMID 39015790, 2024).
Insulin resistance (continued). "TNFα is also involved in inducing insulin resistance; thus, a potential decrease of TNFα signaling by the decrease of inflammatory pathways seen in pigs supplemented with milk might benefit insulin sensitivity." (PMID 39705291, 2024). "There is evidence that an increased level of adiponectines and leptines promotes inflammation, while the pro-inflammatory cytokine TNFα leads to insulin resistance by inhibiting tyrosine kinase activity, which results in a vicious circle affecting cholesterol and triglyceride regulation." (PMID 39335613, 2024). "This could suggest that FLRE and FLLE might reduce inflammation in adipocytes and then suppress insulin resistance in TNF-α-induced adipocytes." (PMID 38543073, 2024). "Additionally, tumor cells can secrete large amounts of IL-6 and TNF-α, leading to insulin resistance and subsequent hyperglycemia." (PMID 39687887, 2024). "Additionally, insulin resistance induces chronic low-grade inflammation, characterized by elevated cytokines such as TNF-α and IL-6, further accelerating GC progression." (PMID 39736510, 2024). "TNFα was the first pro-inflammatory cytokine related to inflammation-induced insulin resistance." (PMID 38953241, 2024). "Taken together, our findings indicate that the 12 h TNF-α/24 h hypoxia treatment of adipocytes results in an adipocyte inflammation/insulin resistance model that can be maintained an additional 48 h in culture after treatment with no further detrimental effect on cell viability." (PMID 39415617, 2024). "Moreover, TNF-α compounds insulin resistance by suppressing key genes involved in adipocyte development and insulin signaling." (PMID 38826152, 2024). "This association may be attributed to overproduction of inflammatory cytokines such as IL-12, IL-23, and TNF-α, which affect systemic metabolism and induce metabolic disorders like insulin resistance." (PMID 39797174, 2024). "Additionally, insulin resistance, a factor associated with NAFLD, and levels of liver inflammatory cytokines TNF-α and IL-6, were also ameliorated with supplementation of silymarin." (PMID 38674860, 2024). "Insulin resistance and lipid disorder could be improved when TNF-alpha level was reduced in diabetic setting." (PMID 38997754, 2024). "Both FLLE and FLRE treatment could reduce insulin resistance in TNF-α-induced adipocytes, which is consistent with a previous study in which ethanolic and methanolic extracts of Ficus deltoidei increased insulin-mediated glucose uptake." (PMID 38543073, 2024). "Furthermore, the activation of IKK-β in the setting of elevated oxidative stress by inflammatory cytokines such as TNF-α in MASLD, is associated with liver insulin resistance." (PMID 39064282, 2024). "Therefore, we undertook a study to establish the hypoxia and TNF-α in vitro model of insulin resistance and inflammation for long-term culture." (PMID 39415617, 2024). "Therefore, the objectives of this study were to investigate the effect of ferulic acid on inflammation and insulin resistance and reveal its mechanism of action in TNF-α-treated 3T3-L1 adipocytes." (PMID 38257186, 2024). "In addition, TNF-α contributes directly to insulin resistance, while IL-17 appears to link psoriasis and hyperglycemia." (PMID 39331218, 2024). "This is primarily caused by the generation of pro-inflammatory cytokines including interleukin-6 (IL-6) and tumor necrosis factor-α (TNF-α), which have significant metabolic effects on insulin resistance and lipid metabolism in addition to inducing inflammation." (PMID 39872862, 2024). "An inflamed visceral fat pad produces pro-inflammatory adipokines including interleukin-1β (IL-1β), interleukin-6 (IL-6), and tumor necrosis factor-α (TNF-α), which contribute to the progression of systemic insulin resistance, type 2 diabetes, MAFLD, heart failure, and atherosclerosis." (PMID 39160276, 2024).
Insulin resistance (continued). "Therefore, one of the pathological reasons for insulin resistance in diabetic cases is elevation of TNF-α, which was also observed in the present investigation." (PMID 38164478, 2024). "Tumor necrosis factor-alpha (TNF-α) in the liver is associated with oxidative stress and may play a role in insulin resistance." (PMID 39683546, 2024). "The redistribution of fat (e.g., loss of subcutaneous fat and increased visceral adiposity) promotes a chronic inflammatory state, marked by increased TNF-α and IL-6, which not only worsens insulin resistance but also disrupts bone health by increasing bone resorption and reducing bone formation." (PMID 39339002, 2024). "Drug-induced insulin resistance was attenuated, and the glucose uptake was four times higher in the presence of 10 ng/mL TNF-α and three times higher in the presence of 1 μg/mL resistin at a deuterium concentration of approximately 50 ppm relative to natural water." (PMID 39200235, 2024). "Additionally, IL6 and TNFα expression are higher in obese individuals with insulin resistance, with TNFα playing a role in insulin resistance." (PMID 38339282, 2024). "In obesity, insulin resistance, and metabolic syndrome, fatty tissue becomes chronically inflamed and secretes increased levels of inflammatory factors such as IL-1β, TNF-α, and IL-6, which stimulate liver inflammation and disrupt glycolipid metabolism through the body circulation." (PMID 38310315, 2024). "Patients with heart disease complicated with T2DM may produce inflammatory cytokines, such as tumor necrosis factor-α and interleukin-6, due to intramuscular fat accumulation, which induces insulin resistance and leads to skeletal muscle catabolism." (PMID 38333459, 2024). "UCSC-EXOs could increase insulin sensitivity by increasing the activation of insulin/AKT signaling pathway and inhibiting the secretion of proinflammatory cytokines like TNF-α, which could reverse insulin resistance in T2DM." (PMID 38720885, 2024). "TNF-α, in particular, is hypothesized to be a pivotal mediator of insulin resistance and metabolic dysfunction, and its elevation is believed to influence the pathogenesis of diabetic complications directly." (PMID 39101085, 2024). "Molecular docking further showed berberine from mSMG had excellent binding capacity with the hub target TNF and might be involved in diabetes and insulin resistance." (PMID 39285464, 2024). "An important factor in the development of insulin resistance is TNF-α." (PMID 38913047, 2024). "However, VAT particularly displays a major role in insulin resistance and TNF, IL-6 mediated adipose tissue inflammation." (PMID 39728000, 2024). "In addition, insulin resistance and glucose intolerance are observed in mice with liver-specific IL-6Rα KO, resulting in increased IL-6, IL-10, and TNF-α expression." (PMID 38999780, 2024). "Targeting TNF-α and/or its receptors may therefore be a promising approach for treating type II diabetes and insulin resistance." (PMID 39468643, 2024). "SFA C 16:0 also increases the production of interleukin (IL) 1β that not only promotes the development of insulin resistance in tumor necrosis factor (TNF)-dependent and TNF-independent pathways, but also activates autophagy by inducing ER stress and causing metabolic dysregulation." (PMID 38459494, 2024). "Thus, by these means, TNF-α accumulation impedes cellular insulin signaling and can eventually result in insulin resistance." (PMID 39201652, 2024). "The role of insulin resistance and the TNF signaling pathway in AMI has also been investigated." (PMID 38890389, 2024). "In summary, leptin, TNF-α, and IL-6 may participate in progressive maternal insulin resistance in pregnancy, whereas the insulin sensitivity-enhancing effect of adiponectin diminishes as its maternal concentrations decrease." (PMID 39519203, 2024).
Insulin resistance (continued). "TNF-α inhibits insulin signaling and insulin-regulated glucose uptake, thus suggesting that the insulin resistance of pregnancy may be mediated through this cytokine." (PMID 39035597, 2024). "Our findings support the hypothesis that chronic inhibition of CXCR2 signals may delay the onset and prevent the development of TNF-a induced insulin resistance and related complications." (PMID 39627194, 2024). "There is evidence that TNFα and IL-6 may promote insulin resistance through pathways that hinder the translocation of glucose transporter 4 (GLUT4) to the plasma membrane." (PMID 38317257, 2024). "We tested whether modulating TNF-α/hypoxia treatment time could reduce cell death while still inducing inflammation and insulin resistance." (PMID 39415617, 2024). "Furthermore, research suggests a bidirectional relationship between periodontitis and insulin resistance, where chronic systemic inflammation exacerbates periodontitis by inducing the expression of tumor necrosis factor-α in periodontal tissues." (PMID 38610162, 2024). "Pro-inflammatory cytokines such as TNF-α are widely used in insulin resistance cell models." (PMID 39749015, 2024). "Insulin resistance in patients with RA may be attributed to the increase in proinflammatory cytokines like TNF-α and IL-6 and the extensive use of GCs during the pandemic, especially for patients with low SpO2 levels." (PMID 39456932, 2024). "Molecular docking further showed berberine from mSMG had excellent binding capacity with TNF-α and might be involved in diabetes and insulin resistance." (PMID 39285464, 2024). "TNF-α is mainly produced in adipocytes and the peripheral tissues and induces tissue-specific inflammation, as well as insulin resistance, through the generation of ROS and activation of various transcriptional mediated pathways, especially mitogen-activated protein kinase (MAPK) pathway." (PMID 38257186, 2024). "CRP, fibrinogen, and ESR were useful, but more specific investigations into aspects such as IL-6 and TNF-α may be necessary to better understand the role of insulin resistance in MetS." (PMID 38731059, 2024). "Furthermore, oxidative stress in adipose tissue produces the adipocytokine TNF-, a pro-inflammatory mediator involved in insulin resistance." (PMID 38266537, 2024). "By contrast, IL-10, which is produced by M2 ATMs, alleviates TNF-α-induced insulin resistance." (PMID 39303983, 2024). "Similarly, persistent elevation of IL-6 and TNF-α, released by adipocytes and muscle cells, can lead to the progression of insulin resistance and subsequently contribute to the onset of metabolic diseases." (PMID 39335642, 2024). "This increased inflammation within the adipose tissue microenvironment has been shown in obese mouse models and is associated with increased cell proliferation and higher levels of inflammatory cytokines, including TNF-alpha, IL-1β and Cox-2, as well as insulin resistance." (PMID 39251829, 2024). "These M1 ATMφs subsequently secreted TNF-α and IL-6, contributing to insulin resistance." (PMID 39063184, 2024). "Anti-TNF-α treatment strategies have been developed to reduce the incidence of insulin resistance." (PMID 39285464, 2024). "It is also known that TNFα is related to the insulin resistance in type 2 diabetes." (PMID 38311861, 2024). "In this study, we hypothesized that ferulic acid improves inflammation and insulin resistance in TNF-α-treated adipocytes." (PMID 38257186, 2024). "While TNF-α is indicative of inflammation and is commonly associated with IR and GDM, there is contrasting evidence on the role of NKT in insulin resistance; however, this is currently based on preclinical evidence in murine models and warrants further exploration in human studies." (PMID 38334487, 2024). "However, it has been reported that insulin resistance and glucose intolerance are improved by eliminating Kupffer cells or neutralizing TNF-α." (PMID 38999780, 2024).